AMD1 (adenosylmethionine decarboxylase 1)
Description:
Essential for biosynthesis of the polyamines spermidine and spermine. Promotes maintenance and self-renewal of embryonic stem cells, by maintaining spermine levels.
Synonyms: AdoMetDC; SAMDC; AMD
Tractability: Small molecule: a structure with a bound ligand is known; a high-quality ligand is known; it has a high-quality binding pocket; it belongs to a druggable protein family. PROTAC: ubiquitination databases record sites on it; a small molecule that binds it is known.
Target class: Enzyme; Lyase
Gene: Protein-coding gene on chromosome 6 (110,874,770 to 110,898,879, forward strand). Ensembl gene ENSG00000123505.
Subcellular location (Human Protein Atlas): Nucleoplasm
Pathways (Reactome):
Metabolism: Metabolism of polyamines
Gene Ontology:
Molecular function: adenosylmethionine decarboxylase activity; identical protein binding; protein binding
Biological process: polyamine metabolic process; spermidine biosynthetic process; spermine biosynthetic process
Cellular component: cytosol
Genetic constraint (gnomAD): Loss-of-function variants: 8 observed, 32.64 expected, observed/expected ratio (o/e) 0.25, 90% interval 0.14 to 0.44. The upper end of that interval is the gene's LOEUF score, 0.44, which puts it in group 1 of 6, group 1 being the genes least tolerant of losing a copy. Missense variants: 212 observed, 359.1 expected, observed/expected ratio (o/e) 0.59, 90% interval 0.53 to 0.66. Synonymous variants: 111 observed, 119.7 expected, observed/expected ratio (o/e) 0.93, 90% interval 0.79 to 1.09.
Homologues: Orthologues: chimpanzee AMD1 (100% identical), macaque AMD1 (99% identical), dog AMD1 (99% identical), mouse Amd1 (98% identical), guinea pig AMD1 (98% identical), mouse Amd2 (98% identical), rat Amd1 (97% identical), zebrafish amd1 (81% identical), tropical clawed frog amd1 (76% identical), Drosophila melanogaster SamDC (50% identical), Caenorhabditis elegans smd-1 (43% identical).
Diseases named in the same sentence as AMD1 in open-access papers:
AMD1 is named in the same sentence as 38 diseases in open-access papers, as found by Europe PMC text mining. Sharing a sentence is not in itself a finding about the gene and the disease. The quoted sentences say what the papers report.
prostate carcinoma (9 papers, 2017 to 2025). A carcinoma that arises from epithelial cells of the prostate gland. "S-adenosylmethionine decarboxylase 1 (AMD1) was upregulated in prostate cancer specimens with activated mTORC1." (PMID 39941741, 2025). "In prostate cancer, the frequent loss of PTEN and activation of mTORC1 leads to increased protein stability of S-adenosylmethionine decarboxylase 1 (AMD1), which catalyzes the production of dcSAM and facilitates polyamine biosynthesis." (PMID 36282248, 2022). "A previous study of a solid tumor (prostate cancer) showed that mTORC1 activation promotes polyamine biosynthesis by stabilizing its regulating enzyme AMD1." (PMID 35243242, 2022). "In prostate cancer, AMD1 regulates the mTOR pathway to influence tumor cell proliferation, thus promoting tumor development." (PMID 33413205, 2021). "SPE2/AMD1 is required for spermidine and spermine biosynthesis, and upregulation of AMD1 by mTORC1 rewires polyamine metabolism in prostate cancer cell lines and mouse models." (PMID 31660150, 2019). "Thus, a PI3K-PTEN-mTORC1 pathway promotes AMD1 protein stability and polyamine biosynthesis in prostate cancer." (PMID 34068137, 2021). "The PTEN-PI3K-mTOR complex 1 (mTORC1) pathway was shown to regulate the stability of SAMDC (AMD1), which controls the use of SAM for polyamine synthesis in prostate cancer." (PMID 36551330, 2022). "Zabala‐Letona found that the up‐regulation of AMD1 could activate the PTEN‐PI3K‐mTORC1 pathway to maintain the growth and proliferation of prostate cancer cells." (PMID 33300278, 2021). "Specifically, metabolomic analyses of tumors from a Pten-deficient prostate cancer (PCa) mouse model, and of human PCa biopsies, revealed increases in dcSAM, N-acetyl-SPD and N-acetyl-SPM, and these changes were linked to increased levels of AMD1 protein but not mRNA." (PMID 34068137, 2021).
neuroblastoma (5 papers, 2012 to 2025). Neuroblastoma (NB) is the most common solid, extracranial childhood tumor. "AMD1 has been shown to be up-regulated following ODC1 inhibition and it has been reported that combined DFMO and SAM486A therapy is synergistic in neuroblastoma." (PMID 23181218, 2012).
breast carcinoma (4 papers, 2021 to 2024). "Given the tight association of AMD1 with breast cancer, it was important to assess whether AMD1 is appropriate as a prognostic factor for breast cancer patients." (PMID 38654332, 2024). "Similarly, high AMD1 expression was closely associated with basal subtype of breast cancer cell lines." (PMID 38654332, 2024). "We first examined the production of spermidine, showing that exogenous AMD1 expression caused a significant increase, whereas knockdown of AMD1 expression resulted in a dramatic decrease in spermidine levels, suggest that AMD1 is required for increased spermidine production in breast cancer cells." (PMID 38654332, 2024). "Clinically, elevated expression of AMD1 was correlated with high grade, metastasis and poor survival, indicating poor prognosis of breast cancer patients." (PMID 38654332, 2024). "The upper quartile survival analysis of the aggregate breast cancer dataset showed that patients with high expression of AMD1 had much lower survival than those with low expression of AMD1." (PMID 38654332, 2024). "Our data showed that low methylation level in promoter regions of AMD1 in breast cancer, especially in BLBC, positively correlated with high expression of AMD1 by analyzing AMD1 methylation and gene expression datasets." (PMID 38654332, 2024). "We then sought to elucidate the association between AMD1 expression and patient survival in NKI295, GES25066 datasets and an aggregate breast cancer dataset by Kaplan-Meier survival analysis." (PMID 38654332, 2024). "We then analyzed Sox10 expression in different subtypes of breast cancer, observing that similar to AMD1, Sox10 was remarkably elevated in BLBC in four gene expression datasets." (PMID 38654332, 2024). "The effect of AMD1 expression on breast cancer cells was evaluated by in vitro and in vivo tumorigenesis model." (PMID 38654332, 2024). "We also analyzed the copy number changes in different subtypes of breast cancer tissues and cell lines, showing that AMD1 copy number amplification was predominantly correlated with BLBC subtype." (PMID 38654332, 2024). "Our data showed that AMD1 significantly induced spermidine production in breast cancer cells, and the spermidine level in BLBC subtype with high AMD1 expression was much higher than that in normal breast tissue and luminal subtype." (PMID 38654332, 2024). "To further investigate the effect of AMD1 expression in tumor cell functions, we examined the effect of AMD1 expression on breast cancer cell proliferation, migration and invasion." (PMID 38654332, 2024). "Additionally, we affirmed these findings by qRT-PCR in different subtypes of breast cancer cell lines, showing that AMD1 mRNA expression was remarkably higher in BLBC cell lines." (PMID 38654332, 2024). "In addition, Methylation-Specific PCR (MSP) analysis showed that the promoter regions of AMD1 in BLBC cell lines had remarkably less enrichment of methylation than that in luminal breast cancer cell lines." (PMID 38654332, 2024). "These clinical data strongly support the critical role of AMD1 in breast cancer aggressiveness." (PMID 38654332, 2024). "AMD1 expression activates the spermidine production and enhances breast cancer cell aggressiveness." (PMID 38654332, 2024). "AMD1 also remarkably affects breast cancer initiation and development." (PMID 33413205, 2021). "To further investigate the correlation between AMD1 expression and basal subtype, we analyzed AMD1 mRNA expression in two gene expression datasets, E-TAMB-181 and E-TAMB-157, containing 56 and 51 breast cancer cell lines, respectively." (PMID 38654332, 2024). "To further explore the clinical relevance of AMD1 expression in breast cancer progression, we assessed the correlation between AMD expression and histological grades of breast cancer patients." (PMID 38654332, 2024). "AMD1 activates TCF4 translation by enhancing spermidine production and eIF5A hypusination of breast cancer cells, promoting breast cancer aggressiveness." (PMID 38654332, 2024).
breast carcinoma (continued). "Indeed, we observed that cases or cells with copy number amplification of AMD1 had much higher AMD1 expression than those without amplification by analyzing copy number variation in breast cancer tissues and cell lines from METABRIC, TCGA and CCLE datasets." (PMID 38654332, 2024).
gastric cancer (4 papers, 2021 to 2023). A primary or metastatic malignant neoplasm involving the stomach. "AMD1, also known as S-adenosylmethionine decarboxylase (AdoMetDC), is one of the key enzymes of polyamine biosynthesis that has a tumorigenic effect on human gastric cancer and affects patient prognosis." (PMID 38049863, 2023). "Furthermore, Xu reported that AMD1 has tumorigenic effects on the prognosis of human gastric cancer, but the potential function of AMD1 in HCC is still unclear." (PMID 33300278, 2021). "The potential function of AMD1 in human gastric cancers is unknown." (PMID 34741681, 2022).
hepatocellular carcinoma (3 papers, 2021 to 2024). A malignant tumor that arises from hepatocytes. "AMD1 is an important regulator in stemness of hepatocellular carcinoma cells." (PMID 36712973, 2022). "Nevertheless, the role AMD1 plays in hepatocellular carcinoma (HCC) is still unknown." (PMID 33783988, 2021).
Obesity (3 papers, 2012 to 2021). Accumulation of substantial excess body fat. "Four common variants involved in inflammatory-adipokine triggering (IL6 rs2069845, LEPR rs1137100, NAMPT rs3801266, and AMD1 rs2796749) have recently been associated with obesity and related traits in Indian children." (PMID 26558825, 2015). "Because of strong association of AMD1 variant rs2796749 with childhood obesity and measures of adiposity, we attempted to replicate the signal obtained at rs2796749 in additional sample set of 1843 children in stage 2." (PMID 22496743, 2012). "In conclusion, we demonstrate here, for the first time, association of AMD1 variant with susceptibility to obesity and measures of adiposity in Indian children." (PMID 22496743, 2012). "Our study provides first evidence for the association of AMD1 variant with obesity and plasma leptin levels in children." (PMID 22496743, 2012). "The study reveals association of AMD1 variant rs2796749 with obesity, measures of adiposity and plasma leptin levels in urban Indian children." (PMID 22496743, 2012). "Although the present study design limits the potential to identify the causal relationships, based on previous studies, we can speculate that AMD1 variant might influence the susceptibility to obesity by modulating either the polyamines metabolism or DNA methylation." (PMID 22496743, 2012). "High AMD1 level could promote SRY‐box transcription factor 2 (SOX2), Kruppel like factor 4 (KLF4), and NANOG expression of HCC cells through obesity–associated protein (FTO)‐mediated mRNA demethylation." (PMID 33783988, 2021). "The IL6, LEPR, NAMPT, and AMD1 gene variants previously found to associate among Indian children did not associate with risk of obesity or obesity-related quantitative measures among Caucasian children and juvenile men from Denmark." (PMID 26558825, 2015). "The current study illustrates that four variants (IL6 rs2069845, LEPR rs1137100, NAMPT rs3801266, and AMD1 rs2796749) implicated in childhood obesity among Indians are not strongly associated with obesity among Danish children and juveniles." (PMID 26558825, 2015).
lymphoma (2 papers, 2021 to 2023). A malignant (clonal) proliferation of B- lymphocytes or T- lymphocytes which involves the lymph nodes, bone marrow and/or extranodal sites. "Researchers found that loss of EIF5A1 and AMD1 cooperate lymphoma progression in mice." (PMID 37047039, 2023). "In lymphoma, AMD1 acts as a tumor suppressor gene by regulating the posttranslational modification of eukaryotic translation initiation factor 5A (eIF5A)." (PMID 33413205, 2021).
melanoma (2 papers, 2024 to 2025). A malignant, usually aggressive tumor composed of atypical, neoplastic melanocytes. "We therefore asked whether AMD1 inhibition can also sensitize melanoma to a combination of vemurafenib and MEK inhibitor trametinib." (PMID 38965534, 2024). "Key molecular targets in this process, including ODC1, AMD1, DHPS and c-Myc could serve as effective drug targets addressing specific vulnerabilities in BRAFi resistant melanoma, warranting development of novel breakthrough therapies against therapy resistant melanoma." (PMID 38965534, 2024).
atopic dermatitis (1 paper, 2025). "Through systematic computational analysis, this study untangles the core molecular network (SPTLC2, AMD1, IGSF3) and the key metal metabolic regulatory axis (copper homeostasis pathway) involved in the pathophysiology of atopic dermatitis (AD)." (PMID 40564068, 2025).
autoimmune disease (1 paper, 2020). A disorder resulting from loss of function or tissue destruction of an organ or multiple organs, arising from humoral or cellular immune responses of the individual to their own tissue constituents. "Some other potential therapeutic targets for treating autoimmune diseases, such as SLE, are the polyamine synthesis (SMS, ODC, AMD1) and recycling (SAT1) enzymes, transglutaminases, peptidyl arginine deiminases (related to NETosis), and EBV genes." (PMID 34968240, 2020).
breast tumors (1 paper, 2024). "To determine whether DNA methylation level was associated with AMD1expression in breast tumors, we analyzed methylation and expression of AMD1 from the TCGA dataset." (PMID 38654332, 2024). "Some breast tumors with AMD1 overexpression were observed to have no AMD1 copy number amplification and hypomethylation of AMD1 promoter, indicating the involvement of other mediators in the upregulation of AMD1 expression." (PMID 38654332, 2024).
colorectal cancer (1 paper, 2016). A primary or metastatic malignant neoplasm that affects the colon or rectum. "The results of coexpression analysis coupled to ENCODE ChIP-Seq data strongly suggest c-Myc and C/EBPβ as regulators of the expression of key enzymes of polyamine metabolism that are upregulated in colorectal cancer: SMOX, AZIN1, MTAP, SRM, AMD1, ODC1, and AGMAT." (PMID 27433286, 2016).
cutaneous melanoma (1 paper, 2020). A primary melanoma arising from atypical melanocytes in the skin. "In addition, hyperactive EZH2 mutations are reported to control cell growth and metastasis through silencing of distinct tumor suppressors, such as DCK, AMD1, and WDR19, in cutaneous melanoma." (PMID 32906688, 2020).
liver cancer (1 paper, 2021). An epithelial or non-epithelial malignant neoplasm that arises from the liver. "However, up to now, there is no research about AMD1 effect on liver cancer, prompting us to investigate its oncological functions and clinical significances in HCC." (PMID 33783988, 2021).
lung carcinoma (1 paper, 2021). "Although there are no clinical researches on AMD1 as a biomarker in HCC, some evidence still remains that the concentration of SPD in plasma differs significantly between HCC and lung cancer patients (at least 40 times)." (PMID 33783988, 2021).
mood disorder (1 paper, 2017). A cognitive disorder a disturbance in which the person's mood is hypothesized to be the main underlying feature. "Another DEG AMD1 (which encodes an intermediate enzyme relevant to the polyamine biosynthesis) has an altered activity in AD and has also been implicated in schizophrenia and mood disorders, and was found up-regulated in affected AD-like O. degus." (PMID 28373841, 2017).
Pruritus (1 paper, 2022). Pruritus is an itch or a sensation that makes a person want to scratch. "LCK, AMD1, and MAPKAPK2 might be possible oxymatrine targets in the treatment of pruritus." (PMID 36210824, 2022).
tumor (17 papers, 2008 to 2026). "Further, AMD1 expression was significantly associated with tumor size (p = 0.037) and preoperative serum alpha‐fetoprotein (AFP) level (p = 0.038)." (PMID 33783988, 2021). "S-adenosylmethionine decarboxylase 1 (AMD1) inhibitors such as SAM486A reduce tumor cell proliferation and migration." (PMID 41715254, 2026). "Using five datasets (GES25066, NKI295, MEBTABRIC, GES7390 and GES22358), in which patients were scored for the tumor grades, we observed that AMD1 was predominantly expressed in high tumor grade, especially in grade III." (PMID 38654332, 2024). "Strikingly, MDA-MB468 and SUM159 cells with knockdown of AMD1 expression significantly inhibited tumor growth in vivo compared with wild-type control cells." (PMID 38654332, 2024). "For instance, in cells overexpressing miR–221, we observed an upregulation of FRAT2, AMD1, and MTHFD1L, genes linked to tumor progression, severity, invasiveness, and worse prognosis." (PMID 38339342, 2024). "Our studies showed that AMD1-mediated metabolic system of polyamine in BLBC cells promoted tumor cell proliferation and tumor growth." (PMID 38654332, 2024). "The inhibition of both ODC and S-adenosylmethionine decarboxylase 1 leads to polyamine depletion and tumor suppression." (PMID 35209071, 2022). "In this study, we first confirmed that the expression of AMD1 was significantly increased in HCC tumor tissues." (PMID 33783988, 2021). "AMD1 expression of tumor tissues was also significantly higher than their paired para‐tumor tissues in protein level (p < 0.0001)." (PMID 33783988, 2021). "As expected, AMD1 knockdown in MHCC97H cells decreased the tumor volume and growth rate compared to controls." (PMID 33783988, 2021). "Equally important, overexpression of S-adenosylmethionine decarboxylase 1 (AMD1) promotes tumor growth by increasing biosynthesis of polyamines, and foci formation anchorage-independent cell growth." (PMID 30397274, 2018). "Additionally, adenosylmethionine decarboxylase 1 (Amd1) upregulates Sry-box transcription factor 2 (Sox2), Kruppel-like factor 4 (Klf4), and Nanog through Fto-mediated mRNA demethylation, maintaining tumor stemness." (PMID 41208876, 2025). "AMD1 has been regarded as an oncogene in several cancers and a potential target for tumor therapy." (PMID 38654332, 2024). "AMD1 is also found to be an oncogene in multiple cancers and a potential target for tumor therapy." (PMID 33783988, 2021). "However, the exact mechanism and function of AMD1 on tumor cells remains largely unclear." (PMID 38654332, 2024). "Our studies showed that AMD1-mediated spermidine biosynthetic pathway in BLBC cells contributed to tumor cell proliferation and tumor growth." (PMID 38654332, 2024). "Examples of regulated genes AMD1 and ODC1 in several cancers, notably PCa, and ODC1, are needed for tumor appearance, and overexpression indicates patient survival." (PMID 36834602, 2023). "Subcutaneous and orthotopic tumor mouse models were constructed to analyze the proliferation and metastasis of HCC cells after AMD1 knockdown or overexpression." (PMID 33783988, 2021). "To determine whether AMD1 affected HCC stemness as well, we performed tumor sphere formation assay in AMD1 overexpressed or downregulated HCC cells." (PMID 33783988, 2021). "However, a targeted shRNA library screen identified EIF5A, AMD1, SRM, and DHS as tumor suppressors in the Eμ-MYC model." (PMID 29799508, 2018). "Aggressive tumor behavior and poor outcome is correlated with high expression of synthetic genes (ODC1, SRM, SMS, AMD1, AZIN1) and low expression of catabolic genes (OAZ1, OAZ2, SAT1, PAOX), and these were identified as direct MYC effects by promoter activity and MYCN binding studies." (PMID 29799508, 2018).